SLC9A9 (solute carrier family 9 member A9)
Description:
Endosomal Na(+), K(+)/H(+) antiporter. Mediates the electroneutral exchange of endosomal luminal H(+) for a cytosolic Na(+) or K(+) (Probable). By facilitating proton efflux, SLC9A9 counteracts the acidity generated by vacuolar (V)-ATPase, thereby limiting luminal acidification. Regulates organellar pH and consequently, e.g., endosome maturation and endocytic trafficking of plasma membrane receptors and neurotransporters. Promotes the recycling of transferrin receptors back to the cell surface to facilitate additional iron uptake in the brain. Regulates synaptic transmission by regulating the luminal pH of axonal endosomes (By similarity). Regulates phagosome lumenal pH, thus affecting phagosome maturation, and consequently, microbicidal activity in macrophages (By similarity). Can also be active at the cell surface of specialized cells, e.g., in the inner ear hair bundles uses the high K(+) of the endolymph to regulate intracellular pH (By similarity).
Synonyms: NHE9; FLJ35613; AUTS16
Tractability: Antibody: UniProt places it where antibodies can reach, with medium confidence; UniProt predicts a signal peptide or a membrane-spanning region; its Gene Ontology location is reachable by antibodies, with medium confidence. PROTAC: ubiquitination databases record sites on it.
Gene: Protein-coding gene on chromosome 3 (143,265,222 to 143,848,485, reverse strand). Ensembl gene ENSG00000181804.
Subcellular location: Late endosome membrane; Early endosome membrane; Recycling endosome membrane; Cell membrane; Cytoplasmic vesicle, phagosome membrane
Pathways (Reactome):
Disease: Defective SLC9A9 causes autism 16 (AUTS16)
Transport of small molecules: Sodium/Proton exchangers
Gene Ontology:
Molecular function: protein binding; potassium:proton antiporter activity; sodium:proton antiporter activity; antiporter activity
Biological process: regulation of intracellular pH; potassium ion transmembrane transport; sodium ion import across plasma membrane; sodium ion transmembrane transport; defense response to bacterium; monoatomic cation transport; phagosome maturation; proton transmembrane transport; regulation of pH; sodium ion transport; transmembrane transport
Cellular component: early endosome; early endosome membrane; late endosome membrane; recycling endosome; recycling endosome membrane; plasma membrane; early phagosome; membrane; phagocytic vesicle membrane
Genetic constraint (gnomAD): Loss-of-function variants: 56 observed, 69.21 expected, observed/expected ratio (o/e) 0.81, 90% interval 0.65 to 1.01. The upper end of that interval is the gene's LOEUF score, 1.01, which puts it in group 4 of 6, group 1 being the genes least tolerant of losing a copy. Missense variants: 736 observed, 774.65 expected, observed/expected ratio (o/e) 0.95, 90% interval 0.89 to 1.01. Synonymous variants: 307 observed, 287.99 expected, observed/expected ratio (o/e) 1.07, 90% interval 0.97 to 1.17.
Gene-disease validity (ClinGen):
ClinGen rates the evidence that SLC9A9 causes each of these diseases.
autism spectrum disorder (autosomal dominant): Disputed. A spectrum of developmental disorders that includes autism, and Asperger syndrome.
Homologues: Orthologues: chimpanzee SLC9A9 (99% identical), macaque SLC9A9 (99% identical), rabbit SLC9A9 (96% identical), guinea pig SLC9A9 (95% identical), dog SLC9A9 (94% identical), pig SLC9A9 (94% identical), mouse Slc9a9 (92% identical), rat Slc9a9 (92% identical), tropical clawed frog slc9a9 (76% identical), Drosophila melanogaster Nhe3 (47% identical), Caenorhabditis elegans nhx-5 (36% identical), Drosophila melanogaster Nhe2 (24% identical), and 3 more. Paralogues in human: SLC9A6 (61% identical), SLC9A7 (61% identical), SLC9A8 (30% identical), SLC9A5 (26% identical), SLC9A3 (26% identical), SLC9A2 (25% identical), SLC9A4 (24% identical), SLC9A1 (23% identical), SLC9C1 (16% identical), SLC9C2 (15% identical).
Diseases named in the same sentence as SLC9A9 in open-access papers:
SLC9A9 is named in the same sentence as 33 diseases in open-access papers, as found by Europe PMC text mining. Sharing a sentence is not in itself a finding about the gene and the disease. The quoted sentences say what the papers report.
autism (12 papers, 2011 to 2023). Persistent deficits in social interaction and communication and interaction as well as a markedly restricted repertoire of activity and interest as well as repetitive patterns of behavior. "SLC9A9-Aβ40TX locus was also implicated in the neuropsychiatric disorders of autism and attention deficit hyperactivity disorder." (PMID 36609403, 2023). "SLC9A9 was also one of the differentially expressed genes across multiple expression data sets that were within 10 cM of an autism-implicated locus." (PMID 25002837, 2014). "Rare variant analysis on a cohort level confirmed the association of five genes with autism (AUTS2, NHS, NSD1, SLC9A9, and VPS13)." (PMID 31134136, 2019). "Significantly greater than expected number of rare variants were detected in 5 of the 101 tested autism-linked genes: AUTS2, NHS, NSD1, SLC9A9, and VPS13B." (PMID 31134136, 2019). "As Nhe3 (SLC9A9 in humans) is only a single gene in a multifaceted genetic etiology of autism, it is likely that the expression of several genes in human autism affects simple and complex cell dynamics, producing similar effects at the neural population level." (PMID 30963913, 2018). "Homozygosity mapping, microarray, and sequencing data from families of autism patients with shared ancestry showed a chromosomal deletion in a potentially regulatory non-coding region upstream of SLC9A9." (PMID 25002837, 2014). "Of note, other SLC family genes, SLC9A9 (MIM 608396), SLC6A4 (MIM 182138), and SLC25A12 (MIM 603667), are causative for autism." (PMID 24297458, 2014).
attention deficit-hyperactivity disorder (7 papers, 2014 to 2023). A disorder characterized by a marked pattern of inattention and/or hyperactivity-impulsivity that is inconsistent with developmental level and clearly interferes with functioning in at least two settings (e.g. at home and at school). "By contrast, variants in SLC9A9/NHE9 are associated with attention deficit hyperactive disorder (ADHD) and autism spectrum disorder with epilepsy (ASD)." (PMID 35547574, 2022). "The spectrum of SLC9A9-associated diseases in humans includes attention deficit hyperactivity disorder (ADHD), autism spectrum disorders (ASDs), epilepsy, multiple sclerosis, and cancer." (PMID 34440402, 2021). "The association of SLC9A9 with inattention, smoking initiation, and alcohol dependence suggests a genetic connection between attention-deficit hyperactivity disorder and addictive behavior." (PMID 25002837, 2014). "Attention deficit hyperactivity disorder (ADHD):SLC9A9 has been associated with ADHD, a heritable neuropsychiatric disorder." (PMID 25002837, 2014).
autism spectrum disorder (6 papers, 2018 to 2022). "NHE9/SLC9A9 gene variants in humans are closely associated with attention deficit hyperactivity disorder (ADHD), autism spectrum disorders, and addiction." (PMID 34445065, 2021). "The Slc9a9 knockout mouse and rat models exhibit autism spectrum disorders‐like behavioural deficits." (PMID 33118634, 2020). "Of most interest was the recent demonstration that links the NHE9 coding gen -Slc9a9- to autism spectrum disorders (ASD)." (PMID 30364044, 2018).
glioma (4 papers, 2017 to 2023). A benign or malignant brain and spinal cord tumor that arises from glial cells (astrocytes, oligodendrocytes, ependymal cells). "Solute carrier family 9 member A9 (SLC9A9) encodes the endosomal Na+/H+ exchanger NHE9, a potential driver of glioma progression." (PMID 37952042, 2023). "Then, through LASSO regression, 5 genes (ADD3, GRHPR, KLF13, RHBDL1 and SLC9A9) closely related to the prognosis of WHO Grade 4 glioma patients were selected." (PMID 37952042, 2023).
Anxiety (2 papers, 2018 to 2022). Intense feelings of nervousness, tension, or panic often arise in response to interpersonal stresses. "Conversely, Slc9a9/Nhe9 KO mice do not show obvious changes in gross hippocampal morphology or impairments in locomotion, anxiety, smell, or pain sensitivity." (PMID 35547574, 2022).
adenoma (1 paper, 2020). A neoplasm arising from the epithelium. "On the other hand, among genes overexpressed in adenomas from female patients, AKAP12 (gravin) is a known tumour suppressor and SLC9A9 is associated with epidermal growth factor (EGF) receptor turnover, EGF itself notably involved in corticotrope tumourigenesis." (PMID 32183012, 2020).
alcohol dependence (1 paper, 2014). Physical and psychological dependence on alcohol. "Furthermore, a family-based GWAS study identified significant associations between SLC9A9 variants and alcohol-dependence phenotypes." (PMID 25002837, 2014).
amyotrophic lateral sclerosis (1 paper, 2023). Amyotrophic lateral sclerosis (ALS) is a neurodegenerative disease characterized by progressive muscular paralysis reflecting degeneration of motor neurons in the primary motor cortex, corticospinal tracts, brainstem and spinal cord. "Interestingly, we also identified a complete proxy of the index variant rs116726862 at SLC9A9-Aβ40TX locus, rs115134872 (D′ = 1, r2 = 1), previously associated with survival in amyotrophic lateral sclerosis." (PMID 36609403, 2023).
preeclampsia (1 paper, 2025). Preeclampsia is a hypertensive disorder of pregnancy that is characterized by new-onset hypertension with proteinuria presenting after 20 weeks of gestation, and depending on mild or severe forms may initially present with severe headache, visual disturbances, and hyperreflexia. "Of all the immune cell-regulated preeclampsia differential genes SLC9A9, SH2B3, SDC3, RCC2, F13A1, CCL2, and CBLB were consistently expressed in two transcriptome datasets, and all were highly expressed in macrophages." (PMID 40216654, 2025). "Lastly, we found that the SLC9A9, SH2B3, SDC3, RCC2, F13A1, CCL2, and CBLB in macrophages were likely to be correlated with preeclampsia." (PMID 40216654, 2025).
cancer (9 papers, 2015 to 2022). A tumor composed of atypical neoplastic, often pleomorphic cells that invade other tissues. "SLC9A9 was overexpressed in CRC specimens and up-regulation of SLC9A9 promotes cancer progression and is involved in poor prognosis in CRC." (PMID 31275360, 2019). "The bar plot generated by GEPIA2 clearly showed that the expressions of SLC9A2, SLC9A3, and SLC9A9 in COAD tissues were obviously lower than those in normal tissues, but SLC9A5 and SLC9A7 in cancer were distinctly higher than those in normal tissues." (PMID 34759967, 2021). "For SLC9A2, 3, 4, 9, they are mostly down-regulated in cancer vs. controls, mostly by SLC9A9 and SLC9A2, while majority of these genes show no changes in their expressions in the activated NPCs vs. controls." (PMID 31071451, 2019).
neurological diseases (5 papers, 2017 to 2025). "NHE9 regulates the luminal pH of endosomes and mutations in SLC9A9 have been associated with neurological disorders such as familial autism, ADHD and epilepsy." (PMID 40155618, 2025).
neurodevelopmental disorder (1 paper, 2020). A behavioral and cognitive disorder with onset during the developmental period that involves impaired or aberrant development of intellectual, motor, or social functions. "Among these genes SLC9A9 was the only one with established mouse models of a neurodevelopmental disorder (ASD)." (PMID 32238911, 2020).
SLC9A9 also shares sentences with these, for which no sentence is quoted: glioblastoma (10 papers); tumor (7); epilepsy (5); multiple sclerosis (3); schizophrenia (3); esophageal squamous cell carcinoma (2); Alzheimer disease (1); bacterial infection (1); cervical cancer (1); Christianson syndrome (1); COVID-19 (1); depression (1); genetic disorder (1); hypopituitarism (1); infection (1); iron-deficiency (1); lung adenocarcinoma (1); melanoma (1); mesenchymal tumors (1); non-alcoholic fatty liver (1); viral infection (1).